CD34 (CD34 molecule)
Diseases named in the same sentence as CD34 in open-access papers (continued):
Sharing a sentence is not in itself a finding about the gene and the disease.
breast carcinoma (120 papers, 1997 to 2026). "Elevated CD34 expression linked to increased endothelial cell proliferation, neovascularization, and enhanced tumor progression by directly promoting breast cancer cell proliferation, migration, and invasion." (PMID 40821783, 2025). "We have previously reported that a low baseline CD34+ CEC level was associated with higher pathological CR in primary breast cancer." (PMID 29131533, 2017). "In all 155 cases of IDC, the stroma showed a complete loss of CD34 fibrocytes except around the vessels, while the surrounding mammary tumor-free tissue disclosed a normal distribution of this cell population." (PMID 25011545, 2014). "In all cases investigated (100%), the stroma of invasive carcinomas showed a complete loss of CD34 fibrocytes, while the surrounding mammary tumor-free tissue disclosed a normal distribution of this cell population." (PMID 23469238, 2013). "Interestingly, some well investigated proteins associated with breast cancer were identified, including notch-4, jagged-1 and CD34." (PMID 29899833, 2018). "In breast carcinoma, the stromal loss of CD34 expression and acquisition of SMA myofibroblastic features may constitute a prerequisite for tumor invasiveness." (PMID 23469238, 2013). "In a recent review, when studies on breast cancer with multivariate analysis that used antibodies to CD31 or CD34 were examined, most revealed a positive association with relapse free survival (RFS) (13 out of 14) and all for overall survival (OS) (12 out of 12)." (PMID 12085206, 2002). "In breast carcinoma, recent data suggest that CD34 fibrocytes undergo morphologic and phenotypic alterations characterized by the adoption of a plump myofibroblast-like appearance and loss of CD34 expression, accompanied by the acquisition of α-smooth muscle actin (SMA) expression." (PMID 23469238, 2013). "While CD34 is another commonly used vascular marker, it is less suitable for quantifying vessels in breast cancer due to its lower specificity, staining not only endothelial cells but also stromal and non-endothelial cells." (PMID 39905431, 2025). "Studies correlated high expression of CD34 with the self-renewal and multi-differentiation potential of breast cancer stem cells." (PMID 40821783, 2025). "For example, Luminal and HER2(+) breast cancers exhibited higher numbers of CD34(+)/CD10(+)/c-Kit(+)/vimentin(+) telocytes than triple-negative breast cancers." (PMID 40724542, 2025). "CD34+ stem cell reconstituted NSG mice were implanted orthotopically with 3 × 106 MDA MB231– luc/GFP breast cancer cells and immediately treated with 2B010 or isotype control weekly for total of 6 doses." (PMID 40632611, 2025). "We considered four scenarios, human brain datasets, human breast cancer only, mixed cancer [breast cancer and liver cancer], and primary myelofibrosis (CD34+), each containing data from multiple heterogeneous sources to merge/integrate." (PMID 39226185, 2024). "Double immunostaining for CD34 and αSMA demonstrated different distribution patterns of both markers in normal and breast cancer tissues." (PMID 39698197, 2024). "The dual immunostaining for CD34 and αSMA demonstrated a distinct expression of both markers in normal and malignant breast cancer tissues." (PMID 39698197, 2024). "We used D2-40 versus CD34 for immunohistochemical labeling of each of the 245 paraffin-embedded breast cancer tissues." (PMID 38771398, 2024). "Materials and methods: Double immunostaining for CD34 and αSMA was conducted on 53 breast cancer cases that were thoroughly characterized in relation to clinicopathologic data." (PMID 39698197, 2024). "CD34+ ECs are described to migrate to lymph nodes and contralateral nascent breast cancer lesions to constitute new vessels, fueling angiogenesis, tumor progression, and metastases." (PMID 39103878, 2024). "Alpha-SMA/CD34 dual-IHC staining revealed breast cancer heterogeneity regarding vessel size, vessel density, and perivascular a-SMA status." (PMID 37222874, 2023).
breast carcinoma (continued). "In summary, our study showed wide variations in the intensity of a-SMA staining across the samples and together with CD34 staining, and revealed high breast cancer heterogeneity regarding vessel size, perivascular a-SMA status, and vessel density." (PMID 37222874, 2023). "Herein, the combination therapy of cimetidine and vitamin C caused the most significant decline in the serum levels of VEGF and expression of CD34 in breast cancer tissues, illustrating its promising anti-angiogenic effect in treating breast cancer." (PMID 35798765, 2022). "Lastly, the antitumor activity of DuoBody-CD3x5T4 was studied in CD34+ hematopoietic stem cell (HSC)–humanized NSG mice (NSG-human immune system [HIS] mice) that were SC implanted with MDA-MB-231 breast cancer cells." (PMID 36271507, 2022). "In an early application of this model, Wege and colleagues co-transplanted CD34+ HSCs and human breast cancer cells in NSG mice and observed tumor growth and dissemination, as well as tumor-specific T cell and NK cell activation." (PMID 35697909, 2022). "All treatments in our study caused a major decrease in the elevated serum levels of VEGF and tissue count of CD34 in Ehrlich-induced breast cancer in mice." (PMID 35798765, 2022). "By staining human breast cancer sections for CD34, we corroborated the results from the bladder cancer samples." (PMID 34359889, 2021). "In contrast, the angiogenic markers PECAM1 and CD34 showed the highest mRNA expression in normal-like breast cancer." (PMID 34219652, 2021). "In breast cancer, while iCAFs (PDGFRB+, ACTA2-, CD34+, MCAM-) were implicated in cytotoxic T cell dysfunction of tripe-negative breast cancer, myCAFs (ecm) and myCAFs (TGFβ) were shown to be the primary resistance elements of immunotherapies." (PMID 34869001, 2021). "This is in line with our initial findings that CD34+ cells from existing peritumoral blood vessels are mobilized to the tumor surrounding in bladder and breast cancer patients." (PMID 34359889, 2021). "Future research targeting the potential diagnostic and therapeutic implications of CD34+ fibroblasts and CAF in breast cancer and especially ILC is a promising field of interest." (PMID 32435886, 2020). "In this study, we found lncRNA NR2F1‐AS1 was positively related with CD31 and CD34 in breast cancer through Pearson's correlation analysis, while lncRNA NR2F1‐AS1 transfection promoted human umbilical vascular endothelial cell (HUVEC) tube formation." (PMID 32548873, 2020). "Endothelial markers, including CD31 and CD34, have been used for confirmation of VI in cancers of other organs, including colorectal, oral cavity, and breast cancers." (PMID 33253282, 2020). "Future research targeting the potential diagnostic and therapeutic implications of CD34+ fibroblasts and CAF in breast cancer, especially ILC, is a promising field of interest." (PMID 32435886, 2020). "The use of a GPER agonists has been shown to increase the levels of claudin-5 in the ischemic CA1 in vivo and also increased levels of CD34 in mouse xenograft models of breast cancer." (PMID 29899833, 2018). "We next co-cultured peripheral blood immature myeloid cells (CD33+CD34+CD15+) from healthy blood donors with the human breast cancer cell line MDA-MB231." (PMID 29973593, 2018). "In melanoma and breast cancer, CD34 low patients with high expression of VE-cadherin exhibited a significant reduction in their survival time (log-rank P = 0.049, log-rank P = 0.019, respectively)." (PMID 27966446, 2017). "One approach to achieve this is by incorporation of immune cells through co-transplantation of human CD34+ hematopoietic stem cells and breast cancer cells in immunodeficient mice." (PMID 28381598, 2017). "Consecutive sections of breast carcinoma samples from 58 patients were stained with CD34 and D240 to stain blood and lymphatic vessels respectively." (PMID 28203117, 2017).
breast carcinoma (continued). "Previous studies demonstrated that MVD which is measured by CD34 was a reliable method to evaluate angiogenesis of breast cancer." (PMID 29228721, 2017). "In liquid tumors, CD34+ cells achieved highest concordance; hESC was superior in lung adenocarcinoma and breast cancer." (PMID 28333954, 2017). "The levels of CD34+ VEGFR2+ EPCs from patients with early-stage breast cancer and benign proliferative breast diseases were higher than that in healthy controls." (PMID 27881867, 2016). "Immunohistochemistry confirmed that CDK11p58 was negatively associated with angiogenesis-related proteins such as VEGF, CD31 and CD34 in breast cancer patients." (PMID 26470709, 2015). "In the nude mouse cancer model and in the breast cancer patient samples assessed by IHC, we also found that CDK11p58 expression was negatively associated with angiogenesis related proteins VEGF, CD31 and CD34." (PMID 26470709, 2015). "Double immunohistochemical staining for CCL18 and CD34/CD31/vWF was performed in 80 breast cancer samples to study the correlation between CCL18+ TAMs and microvascular density (MVD)." (PMID 26416449, 2015). "Immunohistochemistry was used to detect the expression of vascular endothelial growth factor (VEGF), CD31 and CD34 in CDK11 positive patient breast cancer tissues." (PMID 26470709, 2015). "TCs in primary mammary gland stromal cells with long and thin overlapping cytoplasmic processes, expressed c-kit/CD117, CD34 and vimentin in reconstitute breast cancer tissue." (PMID 23206234, 2013). "We performed immunohistochemistry and immunofluorescence staining to determine vimentin+, c-kit/CD117+ and CD34+ TCs in EMT-6/stromal cells reconstituted breast cancer tissue." (PMID 23206234, 2013). "A pathological examination using CD34 of one thousand early-stage primary breast cancer specimens has shown that basal-like breast cancer and TNBCs had significantly higher microvessel densities (MVDs) than the nonbasal and non-TNBC groups." (PMID 22007214, 2012). "Colocalisation of PRL-3 with CD34 in breast cancer tissue was evaluated using confocal laser immunofluorescence." (PMID 16832410, 2006). "In one study of male breast cancer using CD34 to highlight vessels, it was concluded that MVD was an important prognostic tool." (PMID 15743520, 2005). "Blood vessel counts using CD105 are a better prognostic factor than CD34 in patients with breast cancer." (PMID 12799646, 2003). "We conclude that selected CD34+ cells safely support haematopoietic recovery following high-dose chemotherapy in patients with poor-prognosis breast cancer." (PMID 9764583, 1998). "Seventy-one patients with poor-prognosis breast cancer were enrolled after informed consent in a multicentre randomized study to evaluate the use of selected peripheral blood CD34+ cells to support haematopoietic recovery following high-dose chemotherapy." (PMID 9764583, 1998). "During late tumorigenesis, heterogeneous cancer-associated fibroblasts (CAFs) were identified in mouse models of breast cancer, including a population of CD34– myofibroblastic CAFs (myCAFs) that were transcriptionally and phenotypically similar to senescent CAFs." (PMID 40216939, 2025). "CD34– myCAFs express high levels of Lrrc15+, a marker of immunosuppressive fibroblasts that mediates resistance to immune checkpoint blockade in pancreatic cancer, and Col12a1, identified as a potential driver of invasion in breast cancer." (PMID 40216939, 2025). "A previous report has consistently indicated high ENG staining on CD34‐negative stromal fibroblast‐like cells to be associated with poorer outcomes in 56 breast cancer patients." (PMID 40644310, 2025). "In this study, we attempted to utilize CD34 IHC staining to identify LVI in breast cancer." (PMID 38771398, 2024). "In contrast to proteomic studies on CAFs in breast cancer, no consistent association between CD34 expression and CAFs was observed." (PMID 39575252, 2024).
breast carcinoma (continued). "Next, we evaluated the shapes of CD34+-stained blood vessels in human breast cancer (BCA) samples." (PMID 39095583, 2024). "Immunohistochemical staining of breast cancer samples containing lymphovascular invasion using specific vascular endothelial markers D2-40 and CD34 was used to classify lymphovascular invasion and to investigate the relationship between lymphovascular invasion and breast cancer progression." (PMID 38771398, 2024). "DIA was used to compare CD34- and αSMA-positive CAFs among breast cancer molecular subgroups." (PMID 37568639, 2023). "We analyzed MVD through CD34 and vWF, and we found that CD34 and vWF had obvious correlation in breast cancer tissues, which meant that these two indicators could reflect MVD in breast cancer." (PMID 36465358, 2022). "In breast cancer specimens, CD34 expression is reduced and SMA expression is increased within the stroma of high grade ductal carcinoma in situ, which may reflect differentiation of fibrocytes within the developing tumor stroma." (PMID 32731354, 2020). "However, as HLA-A*02 is the most highly prevalent HLA-A allele in patients with melanoma and breast cancer (including tumors cells used in this study), NSG mice were reconstituted with HLA-A*02 CD34+ HSCs." (PMID 29467463, 2018). "To illustrate whether the decreased MRPS23 contributes to breast cancer cell proliferation and angiogenesis, we performed ki-67 and CD34 stain, respectively." (PMID 29069745, 2017). "Finally, an in silico study revealed the association of high VE-cadherin expression with poor survival in a subset of melanoma patients and breast cancer patients showing low CD34 expression." (PMID 27966446, 2017). "CXCR4 antagonists, were first evaluated in the treatment of HIV, later was discovered their potential for mobilizing CD34+ hematopoietic peripheral stem cells, but these classes of drugs are promising anticancer drugs and several clinical trials are ongoing including breast cancer." (PMID 26896000, 2016). "The availability of limited amounts of patient TEM was partially overcome by taking advantage of our recently developed model system of TEM differentiated in vitro by exposing CD34+ cord blood hematopoietic progenitors to breast cancer cell conditioned culture medium." (PMID 25768678, 2015). "The modification of stromal components with the disappearance of CD34 positive fibrocytes and by contrast the acquisition of smooth-muscle actin positive myofibroblasts is a frequent event in breast carcinomas but has been little studied in its metastatic sites." (PMID 25339428, 2014). "The stromal loss of CD34 expression and acquisition of smooth muscle actin (SMA) myofibroblastic features may constitute a prerequisite for tumor invasiveness in breast carcinoma." (PMID 25011545, 2014). "The stromal loss of CD34 expression and acquisition of SMA myofibroblastic features may constitute a prerequisite for tumor invasiveness in breast carcinoma." (PMID 25011545, 2014). "The first one could affect early stages of DC differentiation and could be responsible for the increased frequency of CD34+ cells and decreased number of Lin-/HLA-DR+ DCs observed in the peripheral blood of breast cancer patients." (PMID 14562018, 2003). "But as CD34 has been shown to yield higher microvessel values than CD31 or factor VIII in breast cancer, it might be useful to combine CD34 and CD31 antibodies." (PMID 12232748, 2002). "The state of vascularization in axillary LNs in patients with breast cancer (BC) was assessed by light microscopy using antibodies to the CD34 antigen." (PMID 35330327, 2022). "In our study, we found that lncRNA NR2F1‐AS1 was positively related to the vessel target CD31 and CD34 in breast cancer, and could enhance the tube formation ability of HUVECs in vitro, which hinted the potential role of lncRNA NR2F1‐AS1 in breast cancer angiogenesis." (PMID 32548873, 2020).
breast carcinoma (continued). "To investigate whether SOX4 expression is also associated with increased angiogenesis in patients with human breast cancer, we examined CD34 expression (a marker for small and newly formed blood vessels) in 17 SOX4-low (SOX4LO) and 17 SOX4-high (SOX4HI) ductal carcinomas from our cohort." (PMID 30507376, 2018). "Furthermore, IFDUC1-positive CD34 ADSC could be a contributing metastatic factor as CD34+ ADSC were shown to induce a metastatic shift of breast cancer cell lines in a mouse model." (PMID 26968831, 2016). "In another study, c-Kit(+), CD34(+), and vimentin(+) telocytes promoted the growth of EMT6 breast cancer cells and inhibited apoptosis in vitro." (PMID 40724542, 2025). "We next planned to study the role of EndMT in angiogenesis of breast cancer, then we performed double-IHC staining for EndMT markers (α-SMA, FSP-1, Vimentin, VE-Cadherin and Fibronectin), and MVD (CD34, vWF) on IDC samples." (PMID 36465358, 2022). "To investigate the potential role of neovascularization in breast cancer, we first performed IHC staining for MVD (CD34, vWF), an important quantitation of the neovascularization, on samples from 86 IDC patients." (PMID 36465358, 2022). "To evaluate the impact of MCLA-145 treatment in the context of a more heterogenous T cell population, we engrafted NSG mice with human CD34+ hematopoietic stem cells and then implanted the PD-L1 expressing human MDA-MB-231 breast cancer line." (PMID 34290245, 2021). "We found that high expression of lncRNA NR2F1‐AS1 was correlated with high level of CD34 (P < .05, R = .34) and CD31 (P < .05, R = .30) in breast cancer, which were two vital markers of endothelial cells." (PMID 32548873, 2020). "These heterotypic clusters were detected in melanoma (Melanoma CTCs: CD45−/CD34−/CD90−/CD105−/CD73− but CD146+/MelA+ cells), as well as in breast cancer patients’ blood (Breast cancer CTCs: EpCAM+/PanCK+/DAPI+ but CD45− cells)." (PMID 31003475, 2019). "The observed CD34+ and VEGFR2+ tumor vascular counts in individual breast cancer cases were heterogeneous." (PMID 28533703, 2017). "Since stabilin-1 expression was found on intratumoral vessels in human urothelial bladder cancer and melanoma we have analysed co-expression of stabilin-1 with vascular markers CD34 and CD31 in human breast cancer." (PMID 27105498, 2016). "Protein expression of D2–40, CD34, and VEGF-A was assessed by immunohistochemistry on paraffin-embedded sections of primary breast cancer specimens from 92 patients submitted to SLN investigation." (PMID 19356249, 2009). "The expression pattern of CD45, CD34, CD31 and VWF in both cervical and breast cancer was highly variable between individuals being examined." (PMID 18286204, 2008). "To further confirm that TVECs were defective in phenotype and function, we examined expression of CD45, CD34, CD31 and VWF in the native human cervical and breast cancers." (PMID 18286204, 2008). "Circulating endothelial cells were significantly elevated in breast cancer patients and decreased during chemotherapy, whereas EPC (CD34+/VEGFR-2+) as well as their progenitor cell population CD133+/CD34+ and the population of CD34+ stem cells increased." (PMID 16450002, 2006). "Tissue sections of the primary tumour and a lymph node metastasis of 60 patients with breast cancer were immunohistochemically stained for the hypoxia-markers carbonic anhydrase 9 (CA9), hypoxia-inducible factor-1α (Hif-1α) and DEC-1 and for CD34/Ki-67." (PMID 16251878, 2005). "In a study of 106 patients with breast carcinoma, the IMD was assessed using a pan-endothelial marker CD34 and a monoclonal antibody to CD105 that preferentially reacts with endothelial cells in angiogenic tissues." (PMID 12085206, 2002). "The CD34+ cells confirm the expression of fibroblasts, along with vascular and lymphatic endothelial cells, and CD45+ cells confirm the expression of leukocytes infiltrating cells in breast cancer." (PMID 40821783, 2025).